LMO3 (LIM domain only 3)
Diseases named in the same sentence as LMO3 in open-access papers (continued):
Sharing a sentence is not in itself a finding about the gene and the disease.
astrocytomas (2 papers, 2015 to 2016). "Our studies have shown that miR-101 can induce cell apoptosis or senescence by direct or epigenetic regulation to decrease the high expression levels of hypomethylated LMO3 or CPEB1 in astrocytoma cells." (PMID 26701852, 2016). "Using the Kaplan–Meier method, we found that astrocytoma patients who had overexpression or hypomethylation of LMO3 had poor outcomes." (PMID 25829251, 2015). "Therefore, LMO3 overexpression and hypomethylation can be considered to be potential markers for the prognosis of astrocytomas." (PMID 25829251, 2015). "We identified that hypomethylation is one of the mechanisms of LMO3 overexpression in astrocytomas." (PMID 25829251, 2015). "Our data have verified four new hypomethylated genes, F10, POTEH, LMO3 and CPEB1, and their prognostic values in astrocytomas." (PMID 26701852, 2016). "PRDM16, LMO3 and CPEB1 are hypomethylated genes in astrocytoma cells and because CPEB1 and LMO3 have been confirmed as epigenetic targets of miR-101, we examined the effects of miR-101 on the methylation status of PRDM16 by BSP." (PMID 26701852, 2016).
meningioma (2 papers, 2013 to 2022). A generally slow growing tumor attached to the dura mater. "Our series basically confirmed the brisk expression of LMO3 in meningiomas, while immunopositivity hardly varied in exploratory analyses and correlations with histology or prognosis were not investigated." (PMID 35445910, 2022). "In fact, real-time RT-PCR results suggest much more decreased expression of LMO3 in benign and atypical meningioma than that extracted from the microarray multi-probe data." (PMID 23840654, 2013). "Our results show that metabolic aggressiveness in otherwise histological benign meningioma proceeds mostly through alterations in the expression of genes involved in the regulation of transcription, mainly the LMO3 gene." (PMID 23840654, 2013). "Among all transcription factors, LMO3 showed the highest differences between benignA meningioma and more aggressive benignB and atypical meningioma." (PMID 23840654, 2013). "LMO3 was the gene showing the highest combined under-expression in both benignB and atypical meningioma with respect benignA meningioma." (PMID 23840654, 2013). "We selected LMO3 and 230781_at because they show the highest under-expression and over-expression respectively in both benignB and atypical meningioma with respect benignA meningioma." (PMID 23840654, 2013). "Expression of the corresponding onco- and tumor suppressor genes TRIM58, FAM84B, ELOVL2, MAL2, LMO3, and DIO3 were analyzed and scored by immunohistochemical staining and RT-PCR in samples of 111 meningioma patients." (PMID 35445910, 2022). "As previous reports already demonstrated expression in meningiomas and correlation with histology by microarray analyses and gene arrays, immunohistochemical slides for MAL2 and LMO3 were subjected to interim analyses." (PMID 35445910, 2022). "In line with the microarray data, real-time RT-PCR also showed statistically significant under-expression of LMO3 and ID2 in benignB and atypical meningioma with respect benignA meningioma." (PMID 23840654, 2013). "Recent in vitro analyses revealed a dose-dependent efficiency of DCT also in high-grade meningiomas, with specific DNA demethylation of several onco- or tumor suppressor genes (TRIM58, FAM84B, ELOVL2, MAL2, LMO3, DIO3), which have been hardly investigated in meningiomas yet." (PMID 35445910, 2022). "In meningiomas, three previous studies analyzed MAL2 and LMO3 expression." (PMID 35445910, 2022). "Homeobox protein Hox-B3 (HOXB3), LIM domain only protein 3 (LMO3), Homeobox protein Hox-B6 (HOXB6), Homeobox protein Hox-A3 (HOXA3) and DNA-binding protein inhibitor ID-2 (ID2) showed higher under-expression in benignB with respect benignA meningiomas with a fold change lower than −3." (PMID 23840654, 2013).
cervical cancer (1 paper, 2022). A primary or metastatic malignant neoplasm involving the cervix. "These target genes were crossed with mRNAs that are downregulated by more than fivefold in cervical cancer from The Cancer Genome Atlas (TCGA) database, and 8 target genes were finally obtained (OGN, SCN7A, PGR, PTGER3, FGF7, ADAMTS5, LMO3 and ANK2)." (PMID 35513835, 2022).
Hydrocephalus (1 paper, 2023). Hydrocephalus is an active distension of the ventricular system of the brain resulting from inadequate passage of CSF from its point of production within the cerebral ventricles to its point of absorption into the systemic circulation. "In double transgenic mouse model Tg(Lmo3;Hen2), 15% of either Tg(Lmo3) or Tg(Hen2) pups developed hydrocephalus, whereas all double heterozygote pups presented with hydrocephalus." (PMID 36859317, 2023).
Hypertension (1 paper, 2017). The presence of chronic increased pressure in the systemic arterial system. "Three detected genes were recognized by previous studies, and the other 5 loci/genes (MAN1A1, LMO3, NPAP1/SNRPN, DNAL4, and RNA5SP455/KRT8P5) were novel findings, which had no strong main effect on hypertension and could not be easily identified by single-locus genome-wide studies." (PMID 28642868, 2017).
lung squamous cell carcinoma (1 paper, 2017). "A recent genome-wide analysis of DNA methylation and gene expression changes in lung squamous cell carcinoma identified several methylation-driven genes, including CCDC37, CYTL1, CDO1, SLIT2, LMO3 and SERPINB538." (PMID 28198450, 2017).
Parkinson disease (1 paper, 2020). A progressive degenerative disorder of the central nervous system characterized by loss of dopamine producing neurons in the substantia nigra and the presence of Lewy bodies in the substantia nigra and locus coeruleus. "Additionally, DA2 neurons in both species express ALDH1A, an enzyme involved in the synthesis of retinoic acid, and LMO3, a TF highly enriched in the murine SNc, which functions as a transcriptional co-regulator of PITX3 and has also been suggested to play a role in Parkinson’s disease." (PMID 32733875, 2020).
prostate adenocarcinoma (1 paper, 2022). "Lower expression of LMO3 was observed in various cancer types, including prostate adenocarcinoma (PRAD), compared with normal tissues." (PMID 36199576, 2022).
prostate carcinoma (1 paper, 2022). A carcinoma that arises from epithelial cells of the prostate gland. "The protein expression of LMO3 was further investigated by IHC, and we found that LMO3 was obviously decreased in prostate cancer tissues compared with normal prostate tissues." (PMID 36199576, 2022).
sarcoma (1 paper, 2022). A usually aggressive malignant neoplasm of the soft tissue or bone. "As the figures demonstrated, LMO3 was significantly associated with the prognosis of kidney renal papillary cell carcinoma and sarcoma based on DFS." (PMID 36199576, 2022).
thyroid tumor (1 paper, 2022). A benign or malignant neoplasm affecting the thyroid gland. "Since LMO3 was found to be upregulated in the thyroid tumor, the biological function of LMO3 on PTC progression was investigated in this study." (PMID 35350839, 2022). "Recent research has reported that the expression level of LMO3 was increased in thyroid tumor." (PMID 35350839, 2022).
tumor (21 papers, 2008 to 2025). "Genes found mutated in relapse of patient 1, such as LMO3 or RET, are associated with unfavourable outcome of the disease and tumor progression." (PMID 36037157, 2022). "When LMO3 gets downregulated in PCa, we indeed should confirm its tumor-friendly or tumor-suppressing role with more functional experiments in the near future." (PMID 36199576, 2022). "After adjusting for tumor age or purity, LMO3 expression was markedly correlated with most markers of immune cells in PRAD." (PMID 36199576, 2022). "First, in spite of the fact that we observed that LMO3 was rarely expressed in PCa cell lines, the molecular mechanisms of LMO3 in tumor progression, metastasis, and immune infiltration should be investigated in future studies." (PMID 36199576, 2022). "According to primary therapy outcomes and residual tumor, LMO3 expression was reduced in PRAD patients." (PMID 36199576, 2022). "We found that LMO3 expression was closely related with tumor metastasis related clinicopathological findings and patient prognoses." (PMID 30219064, 2018). "Further studies of LMO3 are warranted for a better understanding of its exact role in tumor cell differentiation and proliferation." (PMID 27184832, 2016). "Our samples examined also did not include any neuronal tissue, so that the further investigation of the LMO3 expression is valuable for understanding its exact role in both normal and tumor cells." (PMID 27184832, 2016). "This is concordance with the present study in which the highest expression of LMO3 was found in the most unfavourable tumour group h3." (PMID 21492432, 2011). "To further confirm whether LMO3 influences these genes in PCa, we compared the expression between normal and tumor samples." (PMID 36199576, 2022). "It was shown that LMO3 was overexpressed in tumor compared to the controls." (PMID 32195177, 2020). "Also, we found that the expression of LMO3 was closely related to patient tumor encapsulation, thrombus, vascular invasion and TNM stage." (PMID 30219064, 2018). "According to miRDB: the microRNA database, miR-181a-5p has 887 target genes, including BCL2, LMO3, PTEN, SNAI2, WIF1, which are related to tumor development, cell cycle control, signal transduction processes, and apoptosis." (PMID 37697308, 2023). "To investigate the relevance of LMO3 with HCC metastasis, we collected HCC, tumor thrombus, CNL and normal liver tissues from the same patients and detected LMO3 expression in these tissues." (PMID 30219064, 2018). "Through immunohistochemical staining and western blotting, we found that LMO3 expression was higher in the HCC and tumor thrombus tissues, and lower in the CNL and normal liver tissues." (PMID 30219064, 2018). "For CA12, GALNT7, LMO3, and SLC43A3 there is good separation in expression between tumor and normal tissue at each dose level as well as a suggestion of opposing trends with dose." (PMID 22848350, 2012). "Moreover, in our study, we investigated the association between miR-181a-5p and miR-630 target genes (BCL2, LMO3, PTEN, SNAI2, WIF1) expression and clinicopathological characteristics as well as survival rates of NSCLC patients in tumor tissue." (PMID 37697308, 2023). "We further constructed gene modules in AT2 (LUAD) and basal (LUSC) cells, which revealed that many tumor-related genes in cells from stage-I patients, including PIGR, AZGP1, BTG2, EGR1, and LMO3 in AT2 cells from LUAD, and AQP3, SPHK1, PPT1, and PDIA6 were found in basal cells from LUSC." (PMID 35027529, 2022). "Spearman correlation analysis supported these associations, showing positive correlations between risk scores and tumor stage, grade, invasion percentage, and expression of RAB10, PRKAA2, and LMO3, and negative correlations with BMI, survival time, and LMLN expression." (PMID 40804485, 2025). "Also notable was the absence of ROR1 and LMO3, both nominated from prior cistrome and/or tumor transcriptome studies." (PMID 26556242, 2015).
tumor (continued). "The student's t-test showed that high expression of LMO3 was significantly associated with ≥1 year of age (p = 0.036), low expression of TrkA (p = 0.003) and MYCN amplification (p = 0.04), but not with the tumor stage (p = 0.17), tumor origin (p = 0.083) and Shimada classification (p = 0.082)." (PMID 21573214, 2011). "Low LMO3 expression was correlated with unfavorable PFS in patients with complete response (CR) and R0 (no residual tumor)." (PMID 36199576, 2022). "Importantly, expression of the other 6 highly related zebrafish lmo family members — lmo2, lmo3, lmo4a, lmo4b, lmo5, lmo6, lmo7a, and lmo7b — was much lower than lmo1 in the GATA/GATA fish and showed no appreciable differences between the 3 tumor genotypes." (PMID 37183825, 2023).
cancer (13 papers, 2012 to 2023). A tumor composed of atypical neoplastic, often pleomorphic cells that invade other tissues. "The loss at 12p12.3 includes LMO3, a key gene implicated in the onset and progression of several cancers." (PMID 25391423, 2015). "In this study, we found that LMO3 was abnormally expressed and associated with the prognosis of many cancers, suggesting that it may be involved in tumorigenesis and development." (PMID 36199576, 2022). "In addition, although LMO3 was abnormally expressed and associated with the prognosis of many cancers, we need to answer whether the abnormal effect of LMO3 on tumorigenesis is direct or indirect." (PMID 36199576, 2022). "LMO3 belongs to the LIM-only group of transcriptional regulators, which have been implicated in cancer through its interactions with other transcription factors." (PMID 23840654, 2013). "The mRNA expression of LMO3 in pan-cancer was first analyzed by the TIMER database." (PMID 36199576, 2022). "To further prove that LMO3 may be a prospective prognostic biomarker, we performed survival maps and Kaplan–Meier survival curves in other cancer types." (PMID 36199576, 2022). "Further, the suppression of LIM domain only 3 (LMO3) expression exerting its actions via the LATS1/Hippo pathway evades invasion and metastasis by cancer cells." (PMID 36033517, 2022). "According to the data, numerous genes (such as H2AFX, CDKN2A, TTF2, IKBKE, and UBE2I) were markedly upregulated in many cancer types, while some genes (such as ARRB1, LMO3, KHDRBS2, CIRBP, and RALYL) were remarkably downregulated in multiple cancer types." (PMID 35003212, 2021).
LMO3 also shares sentences with these, for which no sentence is quoted: breast carcinoma (1 paper); breast neoplasm (1); developmental verbal dyspraxia (1); diffuse large B-cell lymphoma (1); dyslipidemia (1); endometrial cancer (1); ependymoma (1); Hyperglycemia (1); infection (1); Insulin resistance (1); Macrocephaly (1); nonsmall cell lung cancer (1); papillary thyroid carcinoma (1); retinal degeneration (1); synovial sarcoma (1); thyroid cancer (1); type 2 diabetes (1); uterine corpus endometrial carcinoma (1); viral infections (1).